OR52Z1 (olfactory receptor family 52 subfamily Z member 1 (gene/pseudogene))
Description:
Odorant receptor.
Synonyms: OR52Z1P
Gene: Unprocessed pseudogene on chromosome 11 (5,177,714 to 5,178,664, reverse strand). Ensembl gene ENSG00000176748.
Subcellular location: Cell membrane
Pathways (Reactome):
Sensory Perception: Expression and translocation of olfactory receptors